SECTM1 (secreted and transmembrane 1)
Description:
May be involved in thymocyte signaling.
Synonyms: K12; SECTM
Tractability: Antibody: UniProt places it where antibodies can reach, with high confidence; its Gene Ontology location is reachable by antibodies, with high confidence; UniProt predicts a signal peptide or a membrane-spanning region. PROTAC: ubiquitination databases record sites on it.
Gene: Protein-coding gene on chromosome 17 (82,321,024 to 82,335,518, reverse strand). Ensembl gene ENSG00000141574.
Subcellular location: Cell membrane; Secreted
Gene Ontology:
Molecular function: protein binding; receptor ligand activity; cytokine activity
Biological process: positive regulation of canonical NF-kappaB signal transduction; positive regulation of T cell cytokine production; immune response; mesoderm development; signal transduction
Cellular component: extracellular exosome; membrane; plasma membrane; extracellular region; Golgi apparatus
Genetic constraint (gnomAD): Loss-of-function variants: 11 observed, 20.45 expected, observed/expected ratio (o/e) 0.54, 90% interval 0.34 to 0.89. The upper end of that interval is the gene's LOEUF score, 0.89, which puts it in group 3 of 6, group 1 being the genes least tolerant of losing a copy. Missense variants: 297 observed, 335.08 expected, observed/expected ratio (o/e) 0.89, 90% interval 0.81 to 0.98. Synonymous variants: 137 observed, 145.23 expected, observed/expected ratio (o/e) 0.94, 90% interval 0.82 to 1.09.
Homologues: Orthologues: chimpanzee SECTM1 (96% identical), dog SECTM1 (33% identical), rat Sectm1b (32% identical), rat Sectm1a (31% identical), mouse Sectm1a (30% identical), mouse Sectm1b (28% identical).